SLC2A3 (solute carrier family 2 member 3)
Diseases named in the same sentence as SLC2A3 in open-access papers (continued):
Sharing a sentence is not in itself a finding about the gene and the disease.
Sepsis (2 papers, 2023 to 2025). Sepsis is defined as life-threatening organ dysfunction caused by a dysregulated host response to infection. "In our model, four genes (NR3C2, CEACAM1, VNN1, and SLC2A3) were linked to the development of AKI in patients with sepsis." (PMID 40765579, 2025). "Downregulation of SLC2A3 expression in sepsis decreases glucose uptake by kidney cells, leading to insufficient intracellular energy metabolism." (PMID 40765579, 2025).
CADASIL (1 paper, 2020). "To shed light on the mechanism of previously observed lower FDG-PET value in the CADASIL subjects, we investigated gene expression levels of GLUT isoforms [SLC2A2 (GLUT2), SLC2A3 (GLUT3), and SLC2A4 (GLUT4)] in VSMC models of CADASIL and control subjects." (PMID 33101365, 2020).
kidney cancer (1 paper, 2025). Primary or metastatic malignant neoplasm involving the kidney. "In kidney cancer (ccRCC), miR-184 suppresses proliferation, migration, and invasion through downregulation of CCND1 and targeting oncogenic pathways, although sponging by LINC01094 and SLC2A3 promotes tumour progression." (PMID 41379397, 2025).
laryngeal squamous cell carcinoma (1 paper, 2022). A squamous cell carcinoma that arises from the larynx. "Similarly, SLC2A3, which is related to glycolysis, can be used as a marker for the invasion of laryngeal squamous cell carcinoma." (PMID 35573741, 2022).
metastatic tumors (1 paper, 2025). "In metastatic tumors, pathway and TF analyses revealed strong hypoxia-inducible factor-1α–driven hypoxia activation, influencing glycolysis (SLC2A1, SLC2A3, PGK1, PDK1, PGM1, and ALDOA), angiogenesis (ANGPTL4 and ADM), and survival in low oxygen (BNIP3, BNIP3L, and NDRG1)." (PMID 40736012, 2025).
mucous adenocarcinoma (1 paper, 2021). "Moreover, SLC2A3 expression was significant up-regulated in T3 + T4 groups, N1 + N2 groups, TNM III + IV groups, MSI-H groups, lymphatic invasion groups and mucous adenocarcinoma groups." (PMID 34211835, 2021).
osteoporosis (1 paper, 2024). A condition of reduced bone mass, with decreased cortical thickness and a decrease in the number and size of the trabeculae of cancellous bone (but normal chemical composition), resulting in increased fracture incidence. "In this study, the random forest model was used to screen out five key ferroptosis genes, including CP, HAMP, HMOX1, FLT3, and SLC2A3, and these 5 differentially expressed key ferroptosis genes were preliminarily verified in the osteoporosis model constructed." (PMID 38650009, 2024).
Parkinson disease (1 paper, 2015). A progressive degenerative disorder of the central nervous system characterized by loss of dopamine producing neurons in the substantia nigra and the presence of Lewy bodies in the substantia nigra and locus coeruleus. "First, we noticed that several well characterized causal genes for AD (APP, PSEN2 and SORL1), HD (HTT and SLC2A3), and Parkinson's disease (PD) (PARK2, PARK7) were bound by REST in hESCs but not mESCs." (PMID 25990720, 2015).
phospholipidosis (1 paper, 2024). "SLC2A3 has been associated with the Nrf2 pathway and found to be upregulated during phospholipidosis." (PMID 38992651, 2024). "The upregulation of SLC2A3, out of the 12 phospholipidosis-related genes, highlights the significant impact of CV on phospholipidosis." (PMID 38992651, 2024).
preeclampsia (1 paper, 2022). Preeclampsia is a hypertensive disorder of pregnancy that is characterized by new-onset hypertension with proteinuria presenting after 20 weeks of gestation, and depending on mild or severe forms may initially present with severe headache, visual disturbances, and hyperreflexia. "In addition, our STRING analysis revealed the potential for interaction between glucose transporter GLUT1 and GLUT3 (SLC2A1, SLC2A3) and inflammatory mediators enriched in the plasma of preeclampsia patients." (PMID 35455936, 2022).
prostate tumors (1 paper, 2022). "Here, we characterize the glucose transporter GLUT3/SLC2A3 as a biomarker of hypoxic prostate epithelial cells and prostate tumors." (PMID 35328229, 2022).
pulmonary fibrosis (1 paper, 2021). Chronic progressive interstitial lung disorder characterized by the replacement of the lung tissue by connective tissue, leading to progressive dyspnea, respiratory failure, or right heart failure. "Four aging-associated core genes (Slc2a3, Fga, Hp, and Thbs1) were related to the development of pulmonary fibrosis." (PMID 34746180, 2021). "We also identified four aging-associated core genes (Slc2a3, Fga, Hp, and Thbs1) related to the development of pulmonary fibrosis." (PMID 34746180, 2021). "Slc2a3, mediating the uptake of various monosaccharides, was reported to be associated with pulmonary fibrosis." (PMID 34746180, 2021).
steatosis (1 paper, 2024). Increased lipid within the cytoplasm of cells. "On the other hand, two genes (CYP1A2 and FMO1) were downregulated in hepatotoxicity pathway, two genes (SREBF1 and FASN) in steatosis, one each in necrosis (IPO4) and phospholipidosis (SLC2A3) pathways." (PMID 38992651, 2024).
velocardiofacial syndrome (1 paper, 2023). "For example, the frequency of congenital heart lesions is increased in individuals with velocardiofacial syndrome who have 22q1.2 deletions and a common 12p13.31 duplication involving the SLC2A3 gene." (PMID 37961530, 2023).
yolk sac tumour (1 paper, 2020). "Increased SLC2A3 expression is reported in TGCTs compared to normal testis, and validated as a sensitive and specific marker for the EC and yolk sac tumour histological subtypes." (PMID 32580154, 2020).
tumor (224 papers, 2008 to 2026). "Solute carrier family 2 member 3 (SLC2A3), a key glucose transporter, has been implicated in tumor metabolism and immune regulation, but its specific role in kidney renal clear cell carcinoma (KIRC) remains largely unclear." (PMID 41268544, 2025). "This indicates that high expression of SLC2A3 is associated with two immune escape mechanisms: dysfunction of tumor-infiltrating cytotoxic T lymphocytes (CTLs) and CTL rejection by immunosuppressive factors." (PMID 38778609, 2025). "Our findings revealed that SLC2A3 expression is closely linked to genomic heterogeneity and tumor stemness, suggesting a role in modulating tumor adaptability under therapeutic pressure." (PMID 41268544, 2025). "SLC2A3 shows aberrant expression across multiple cancers and is strongly associated with patient outcomes, tumor heterogeneity, and immune microenvironment features." (PMID 41268544, 2025). "In this study, we focused on SLC2A3 and demonstrated its contribution to tumor-associated biological processes." (PMID 41268544, 2025). "In contrast, across most tumor types, SLC2A3 expression demonstrated positive associations with macrophages, helper T cells, Th1, Th2, and regulatory T cells (Tregs), while exhibiting a negative correlation with Th17 cells." (PMID 41268544, 2025). "The ferroptosis‐related gene SLC2A3 is associated with tumour immune response and patient prognosis." (PMID 39865544, 2025). "Conclusively, we screened SLC2A3, a hub gene associated with tumor immune microenvironment alteration and prognostic values, using immunological algorithms and clinicopathological characteristics." (PMID 38778609, 2025). "Further evaluation of the tumor microenvironment revealed positive associations between SLC2A3 and StromalScore, ImmuneScore, and ESTIMATEScore, except in TGCT." (PMID 41268544, 2025). "The Glut1-encoding gene Slc2a1 was predominantly expressed in tumor cells, whereas the Glut3-encoding gene Slc2a3 was expressed weakly in tumor cells but strongly in immune cells, particularly myeloid cells." (PMID 39545407, 2024). "Consistent with prior results, we found that tumor cells mostly expressed the Glut1-encoding gene Slc2a1, whereas myeloid cells predominantly expressed Slc2a3." (PMID 39545407, 2024). "Fernanda’s IHC analysis confirms high SLC2A3 expression is associated with advanced tumor stages, vascular invasion, and decreased disease-free survival." (PMID 38625978, 2024). "Of note, CRTC2-CA or CREB-CA normalized TRPM7 deficiency-induced defects in tumor growth, glucose consumption, as well as SLC2A3 expression." (PMID 36878949, 2023). "Inevitably, the protein expression levels of these two high-risk genes (SLC2A3 and UPK3b) were significantly increased in tumor samples, with more obvious antibody staining and higher percentage of stained tissues." (PMID 36246625, 2022). "Among the identified genes, ALDOB was associated with a low risk, while five genes (GPC1, ALDOC, ENO2, SERPINE1, and SLC2A3) were associated with a high risk of developing tumor malignancy." (PMID 33737938, 2021). "Earlier studies together with our mRNA expression analyses and a meta-analysis of hypoxia-inducible genes suggest that expression of SLC2A3/GLUT3 is induced in tumor cells and under control of many tumor-associated pathways including the HIF-pathway." (PMID 31690629, 2020). "Oligonucleotide microarray analysis revealed that SLC2A3 (gene encoded GLUT3) overexpression was correlated with tumor size, pathologic stage and recurrence in oral tongue carcinoma." (PMID 22270867, 2012). "Prior research has primarily concentrated on clinical prognosis and has pointed out that overexpression of SLC2A3 is prominently associated with worse prognosis, such as increased depth of invasion, larger tumor size, advanced pathological stage, recurrence, and vascular embolization." (PMID 38625978, 2024).
tumor (continued). "Consequently, these two cell lines with depressed glucose uptake caused by SLC2A3 depletion developed significantly smaller and lighter tumours than control cells." (PMID 32873793, 2020). "Pan-cancer analysis indicates that SLC2A3 is aberrantly expressed across multiple tumor types and correlates with poor clinical outcomes, highlighting its potential as a universal marker of metabolic reprogramming and immune regulation in cancer." (PMID 41268544, 2025). "Dead patients and patients with higher T, N stage, clinical stage, and tumor grade had higher SLC2A3 mRNA expression." (PMID 38778609, 2025). "Patients who were tumor-free at the last contact or time of death (n = 340, 70.8%) exhibited significantly lower SLC2A3 expression compared to those with active tumors (n = 140, 29.2%)." (PMID 40141095, 2025). "Mechanistically, SLC2A3 is often overexpressed in various cancers and facilitates tumor progression by enhancing glucose uptake and activating NF-κB/EMT signaling." (PMID 41268544, 2025). "Approximately half of the tumor cells or less demonstrated high expression of Syt4, Ankd37, and Slc2a3." (PMID 41009560, 2025). "SLC2A3 exhibits significant prognostic value across various cancers, but its impact is highly tumor-type dependent." (PMID 41268544, 2025). "Lactate production from SLC2A3 promoted tumor growth and invasion, highlighting the SLC2A3/LA/TGF-β regulatory axis in OSCC." (PMID 40362545, 2025). "Comparative analysis of tumor and adjacent normal tissues revealed that SLC2A3 expression was significantly upregulated in eight cancer types, including STES, KIPAN, STAD, HNSC, KIRC, PAAD, TGCT, and CHOL." (PMID 41268544, 2025). "SLC2A3 expression was altered in multiple cancers, being upregulated in eight tumor types and downregulated in twenty." (PMID 41268544, 2025). "For DSS, high SLC2A3 predicted unfavorable survival in 13 tumor types, while decreased expression correlated with poor prognosis in PRAD." (PMID 41268544, 2025). "Under conditions of low glucose, the AMPK/CREB1 signaling pathway is activated in tumor cells, resulting in upregulation of SLC2A3 and creating a positive feedback regulatory loop." (PMID 38778609, 2025). "In ESTIMATE, the high expression group of SLC2A3 showed higher scores for stromal cell and immune cell infiltration, as well as lower tumor purity." (PMID 38778609, 2025). "Among patients with high SLC2A3 expression (n = 55), 49.1% had an active tumor at the last contact or time of death." (PMID 40141095, 2025). "In recent years, SLC2A3 has been highly expressed in various tumor types, including HNSCC, and its expression level is closely correlated with patient prognosis." (PMID 40821122, 2025). "In terms of tumor metastasis, high SLC2A3 expression was primarily associated with enrichment in the EMT, which is crucial for enhancing tumor cell aggressiveness and metastasis." (PMID 38778609, 2025). "This tumor-type specificity likely reflects functional differences of SLC2A3 across tissues and microenvironments." (PMID 41268544, 2025). "Significant differences in SLC2A3 transcriptional expression were observed among patients in the TCGA cohort based on tumor status (p = 0.044)." (PMID 40141095, 2025). "This analysis suggests that the SLC2A3 high-expression group has a more complex tumor microenvironment and a greater potential regulation." (PMID 38778609, 2025). "According to our results, the joint assessment of SLC2A3 and SDHA transcriptional expression allowed us to define a group of patients with an elevated risk of local tumor recurrence after treatment with RT or CRT." (PMID 40141095, 2025). "Specifically, higher transcriptional expression of SLC2A3 and SDHA was associated with an increased likelihood of having an active tumor at the last contact or time of death." (PMID 40141095, 2025).
tumor (continued). "The aerobic glycolysis driven by SLC2A3 not only enhances tumor cell aggressiveness but also initiates a feedback loop that contributes to glucose deficiency in the tumor microenvironment, thereby regulating the inflammatory state of the TME." (PMID 38778609, 2025). "As a key glucose transporter, SLC2A3 regulates cellular metabolism, energy homeostasis, and signal transduction in diverse cancer types, drawing increasing attention for its role in tumor biology." (PMID 41268544, 2025). "There were significant differences in the SLC2A3 transcriptional expression according to the local tumor control after RT or CRT." (PMID 40141095, 2025). "For MSI, SLC2A3 expression was positively correlated in four tumor types and negatively correlated in five." (PMID 41268544, 2025). "The findings demonstrated that tumor volume and weight significantly increased in the mice injected with SLC2A3-overexpressing cells." (PMID 38625978, 2024). "Its targets have been reported to be IL-8, COL1A1, ADAM9, HMGB1, and SLC2A3, and inducing mir-129-5p overexpression in tumor cells reduced malignant characteristics, including cell proliferation, migration, and invasion." (PMID 39797181, 2024). "Our in vivo experiments confirmed that SLC2A3 overexpression promoted tumor growth and metastasis while knockdown inhibited it." (PMID 38625978, 2024). "SCC9 and SAS cells, engineered to overexpress or knock down SLC2A3, were subcutaneously injected into BALb/c nude mice, and subsequent tumor volume and weight measurements were recorded." (PMID 38625978, 2024). "This suggests that SLC2A3 plays a pivotal role in regulating glucose metabolism, thereby fueling the proliferation of tumor cells." (PMID 38625978, 2024). "Consistent with our findings, studies have indicated changes in the ECM of SLC2A3 overexpressed cells, including upregulation of osteopontin, which has been shown to mediate cell adhesion and promote tumor metastasis." (PMID 37621680, 2023). "In BCa, SLC2A3 suppression inhibited tumor cell glucose uptake and proliferation and promoted cell apoptosis." (PMID 36902193, 2023). "For instance, miR-3174 (targeting SNRPA1 mRNA) exhibits oncogenic activity, whereas miR-34a-5p and hsa-miR-644a (targeting SLC2A3 and C8orf37 mRNAs, respectively) possess tumor-suppressive properties." (PMID 36497462, 2022). "The family gene of solute carrier family two member 3 (SLC2A3) is a central regulator of cellular glucose metabolism, but its role in tumor metabolism and immunity has been neglected." (PMID 35923703, 2022). "This further demonstrates the important role of SLC2A3 in predicting tumor prognosis; however, the precise mechanism remains elusive." (PMID 35957685, 2022). "In the present study, we identified the differential expression levels of SLC2A3 gene and protein between tumor tissues and normal tissues based on The Cancer Genome Atlas (TCGA) and several online databases." (PMID 36247875, 2022). "First, the expression of SLC2A3 was analyzed in tumor and adjacent normal tissues in the TCGA and combined GEO datasets." (PMID 35957685, 2022). "Compared with the adjacent normal tissues, SLC2A3 was highly expressed in tumor tissues in both TCGA (p < 0.001) and GEO datasets (p < 0.0001)." (PMID 35957685, 2022). "Further investigation on tumor SLC2A3 expression should be conducted to develop a more comprehensive understanding of SLC2A3 and vitamin C in cancer–nerve crosstalk." (PMID 35565690, 2022). "The Slc2a family, consisting of the genes Slc2a3, Slc2a4, Slc2a5, Slc2a6 and Slc2a7, is responsible for glucose transporters, and exhibited increased transcription in WT type mice tumor compared to KO tumor." (PMID 34685767, 2021). "For validation, we collected 174 CRC samples and found that SLC2A3 expression was higher in CRC tissues than that in adjacent non-tumor colorectal mucosa tissues by immunohistochemistry staining." (PMID 34211835, 2021).